FNDC9 (fibronectin type III domain containing 9)
Synonyms: C5orf40; MGC27121
Tractability: Antibody: UniProt predicts a signal peptide or a membrane-spanning region.
Gene: Protein-coding gene on chromosome 5 (157,341,598 to 157,345,677, reverse strand). Ensembl gene ENSG00000172568.
Subcellular location: Membrane
Gene Ontology:
Molecular function: protein binding
Cellular component: membrane
Genetic constraint (gnomAD): Loss-of-function variants: 3 observed, 9.65 expected, observed/expected ratio (o/e) 0.31, 90% interval 0.14 to 0.8. That is too few expected variants to judge how well the gene tolerates losing a copy. Missense variants: 279 observed, 301.86 expected, observed/expected ratio (o/e) 0.92, 90% interval 0.84 to 1.02. Synonymous variants: 114 observed, 121.61 expected, observed/expected ratio (o/e) 0.94, 90% interval 0.8 to 1.1.
Homologues: Orthologues: chimpanzee FNDC9 (99% identical), macaque FNDC9 (98% identical), dog FNDC9 (92% identical), guinea pig FNDC9 (90% identical), pig FNDC9 (88% identical), rat Fndc9 (86% identical), rabbit FNDC9 (85% identical), mouse Fndc9 (85% identical).
Diseases named in the same sentence as FNDC9 in open-access papers:
FNDC9 is named in the same sentence as 1 disease in open-access papers, as found by Europe PMC text mining. Sharing a sentence is not in itself a finding about the gene and the disease. The quoted sentences say what the papers report.
cancer (1 paper, 2020). A tumor composed of atypical neoplastic, often pleomorphic cells that invade other tissues. "FNDC9 which exhibits biased expressed in the brain is an ECM protein involved in tumorigenesis in different cancers." (PMID 33245713, 2020).